TSPAN8 (tetraspanin 8)
Diseases named in the same sentence as TSPAN8 in open-access papers (continued):
Sharing a sentence is not in itself a finding about the gene and the disease.
tumor (continued). "Additionally, TSPAN8-competent exosomes derived from tumor cells were also shown to promote matrix degradation and shape the tumor microenvironment, which in turn favored tumor growth and metastasis." (PMID 38275818, 2024). "In addition, the results indirectly indicate that, despite the low representation of the CD151+Tspan8+ subpopulation (about 3%) of exosomes, it is they that contribute to the transfer of signals from cancer cells to recipient cells and thus, to tumor dissemination itself." (PMID 36613908, 2022). "However, why and how TSPAN8 expression is switched on during tumor progression are ill-defined." (PMID 34163029, 2021). "Furthermore, Tspan8 mediates tumor cell motility and invasion." (PMID 28977990, 2017). "As tetraspanins are constitutive exosome components and known to be engaged in exosome binding and uptake, we speculated that the metastasis-promoting tetraspanins CD151 and Tspan8 could play a central role in the process of tumor exosome-mediated host modulation." (PMID 25544774, 2015). "In the tumor compartment, several tetraspanins (CD9, CD151, TSPAN1, TSPAN3, TSPAN8, and TSPAN13) were specifically overexpressed, suggesting their involvement in tumor growth and proliferation in stage 4 primary CC." (PMID 38255741, 2024). "Silencing Tspan8 significantly abolished AEG-1-induced metastasis of cancer cells, and decreased the tumor volume in xenograft mice models, possibly by suppressing angiogenesis." (PMID 38389703, 2024). "CD9, CD151, TSPAN1, TSPAN3, TSPAN8, and TSPAN13 displayed specific overexpression in the tumor compartment, indicating potential roles in tumor growth." (PMID 38255741, 2024). "Since miR-24 is a CD44 target, and Tspan8 expression on the surface of some tumor cell cultures is mediated by CD44, we also suggested an indirect relationship between miR-24 and Tspan8 in OC progression." (PMID 36613908, 2022). "To determine the clinical relevance of TSPAN8 in PDAC metastasis, we performed IHC staining of primary tumor and liver metastasis tissues from 17 PDAC patients." (PMID 34163029, 2021). "Two tetraspanins, CD151 and tetraspanin 8 (also known as CO-029 and TM4SF3 in human, and D6.1A in rats), are upregulated in PDAC and support tumour progression." (PMID 34671031, 2021). "Other potential targets in PDA tumor cells derived-EVs include tetraspanins CD151 and Tspan8, which were found to impact several aspects of lung niches, including immune cells, fibroblasts, matrix and EMT." (PMID 34207163, 2021). "For other tetraspanins, such as TSPAN8 and CDC151, antibody-based targeting has been proven to be an effective strategy with which to suppress tumor progression and metastasis." (PMID 34771537, 2021). "In fact, this scenario highly resembles the well-established established tumor-suppressive role of tetraspanins CD82, CD9, and TSPAN8 in epithelial-origin cancers, whereby they regulate E-cadherin/β-catenin complex-dependent cell-cell adhesion." (PMID 33919420, 2021). "Genes related to tumor progression, including matrix metallopeptidase 1 or MMP1, S100 calcium binding protein A2 or S100A2, tetraspanin 8 or TSPAN8, and insulin like growth factor binding protein 7 or IGFBP7 were upregulated in GSM3516665-subgroup 2." (PMID 33170151, 2020). "We intratumorally injected lentivirus expressing TSPAN8-shRNA, which inhibited MDA-MB-231 cell-derived tumor growth in mice." (PMID 31253779, 2019). "TSPAN8 knock-down in the HCCLM3-shTSPAN8 group resulted in a significant decrease in tumor size compared to controls, while TSPAN8 over-expression in the SMMC-7721-TSPAN8 group resulted in a significant increase in tumor size (P < 0.05)." (PMID 27270327, 2016). "Though these activities are generally fitting a contribution to tumor progression, only CD151 and Tspan8 were described as metastasis-promoting in several tumor systems, with no opposing findings reported so far." (PMID 25544774, 2015).
tumor (continued). "Nonetheless, as revealed by flow cytometry of dispersed organs after double staining with anti-EpC and anti-Tspan8, draining LN of HT29-cld7kd-bearing mice contained few tumor cells." (PMID 25514462, 2015). "Further, exosomes derived from CD151- and TSPAN8-competent tumor cells can be transferred into neighboring non-metastatic tumor cells, which induces expression of EMT-related genes." (PMID 38954230, 2024). "Tspan8 and CD151 tetraspanins have been shown to contribute to tumor progression." (PMID 33773551, 2021). "Additionally, while it appears that the role of CD9 in promoting or inhibiting tumor progression is rather controversial, CD151 and TSPAN8 are believed to be involved in tumor progression, displaying rather oncogenic properties." (PMID 34830819, 2021). "Interestingly these impaired phenomena in knockout mice can be mitigated by Tspan8/CD151-competent serum exosomes, through stimulating GPCR and RTK-dependent angiogenesis which ultimately contribute to tumour progression in vivo." (PMID 34671031, 2021). "Deep sequencing revealed altered mRNA and miRNA expression profiles of non-CIC following PDA tumor cells derived-EVs treatment, phenotypically translating to Cd44v6 and Tspan8 concerted non-CIC activation, apoptosis resistance, EMT and higher motility." (PMID 34207163, 2021). "Tspan8 can significantly enhance the targeting of exosomal Cld7-related miRNAs to PaCa sites, leading to decreased Cld7 levels and further reduction on the expression of other CIC markers and Notch1, which suppress tumor cell growth, motility, and invasion." (PMID 32878635, 2020). "The functional role of TSPAN8 is enhancing invasive outgrowth from tumor spheroids within matrigel without affecting cell proliferation or survival." (PMID 32138170, 2020). "We detected Tspan8, CD9, and CD81 signals on EVs isolated in control and in tumour‐bearing animals." (PMID 30982971, 2019). "EPCAM and TSPAN8 showed inconsistent trend in ATC tissues, which may result from the heterogeneity between cell line data and tumor tissue data." (PMID 31183379, 2019). "Statistical analysis demonstrated a slightly higher colony‐forming ability of the MTPa‐pcDNA3 cells compared with the MTPa‐Tspan8 cells, suggesting that Tspan8 does not enhance the self‐sufficiency of tumour cells under conventional cell culture conditions." (PMID 30982971, 2019). "No Tspan8 signal was observed in the livers of rats harbouring the MTPa tumour; the metastases‐free spleen exhibited strong fluorescence of endogenous Tspan8." (PMID 30982971, 2019). "Unlike other tetraspanins, Tspan8 is expressed in a limited number of normal tissues and its mechanism of action in modulating tumor progression is still poorly documented." (PMID 28188308, 2017). "To address the in vivo biologic relevance of these in vitro findings, we orthotopically xenografted non-invasive IC8 cells stably expressing ectopic Tspan8 and invasive T1C3 cells stably silenced for endogenous Tspan8, and examined tumor development rate and P-ILK expression in subcutaneous tumors." (PMID 28188308, 2017). "Of note, our studies of HCC patients indicated that TSPAN8 expression was not correlated with tumor size." (PMID 27270327, 2016). "More importantly, the functional role of TSPAN8 was demonstrated by silencing endogenous TSPAN8 with siRNA, which reduces invasive outgrowth from tumour spheroids within matrigel, without impact on the cell proliferation and survival." (PMID 21081927, 2011). "The functional role of TSPAN8 was demonstrated by silencing endogenous TSPAN8 with siRNA, reducing invasive outgrowth from tumour spheroids within matrigel without affecting cell proliferation or survival." (PMID 21081927, 2011). "Studies involving the transplantation of TSPAN8 and CD151 single- and double-knockout cancer cells into wild-type or autochthonous and syngeneic recipient mice have further unraveled the complex roles of these tetraspanins in host- versus tumor-derived exosomes." (PMID 38275818, 2024).
tumor (continued). "Interestingly, various subtypes of cancer-associated fibroblasts (CAFs)—an important stromal cell population in the tumor microenvironment that assists in EMT, the invasion of cancer cells and cancer metastasis—are characterized by high TSPAN8 expression in high-grade serous ovarian cancer (HGSOC)." (PMID 38275818, 2024). "We surmise that Tspan8/Thrsp upregulation could be an early response which is not sustained during tumour progression." (PMID 37626143, 2023). "Notably, it was shown that rat aortic epithelial cells acquired EVs derived from PC cells and that some proteins included in them, in particular Tetraspanins 8 (Tspan8), CD106 and CD49d, stimulate neovascularization, a process essential for angiogenesis and tumor growth." (PMID 34205944, 2021). "Thus, the close relationship between the tetraspanin family and tumor neoangiogenesis, CD151, and TSPAN8 may represent potential therapeutic targets of HCC in the future." (PMID 34540692, 2021). "In non-CIC, knockdown of CD44v6 downregulated Tspan8, thus inhibiting tumor progression." (PMID 34094979, 2021). "In this model, TSPAN8 was expressed significantly higher in the brain‐seeking 231‐BR cells than in the parental and the 231‐BSC60 cells, indicating that expression of TSPAN8 may vary in the primary tumour and its metastases." (PMID 30982971, 2019). "Immunohistochemistry showed Tspan8 staining in the MTPa‐Tspan8 but not in the MTPa primary tumours." (PMID 30982971, 2019). "However, in vivo studies in mouse cancer models suggest that TSPAN8 enhances cancer cell motility and migration mainly by recruiting integrins, whereas CD151 efficiently recruits and activates MMP9 and MMP13 to facilitate the degradation of the ECM and the invasion of tumor cells." (PMID 38275818, 2024). "Interestingly, the antibodies were highly selective in inhibiting sprouting endothelial cells and were effective regardless of whether the tumor cells themselves expressed TSPAN8 or not." (PMID 38275818, 2024). "Thus, the correlation between TSPAN8 level and tumor size is not obvious." (PMID 34540692, 2021). "Besides elaborating the role of tetraspanins/Tspan8 in routing EE towards MVB and the suggested deviation from degradation in the proteasome, the central importance of CD44v6 in furnishing TEX to cover multiple aspects of tumor progression demands clarification." (PMID 31485223, 2019). "Deciphering the role of exosomal CD151 and Tspan8 revealed that both tetraspanins contribute to matrix degradation that supports tumor and host cell motility, affect stroma and hematopoietic cells and are engaged in a feedback towards non-metastatic tumor cells, where they promote EMT." (PMID 25544774, 2015). "According to this analysis, there was a statistically significant increase in level of expression of GSTM1 and TSPAN8, but not GAGE12J and SNORD59B in the tumor tissue samples obtained from Black patients." (PMID 36812168, 2023). "The data showed an increase in TSPAN8 expression, but not THRSP expression, in BRCA2-mutant tumours compared with wild-type tumours." (PMID 37626143, 2023). "CD44v6 and Tspan8 are PaCIC-biomarkers, with message delivery by CIC-TEX being expected to convert nonmetastasizing tumor cells into CIC." (PMID 31485223, 2019). "To further examine the role of TSPAN8- and ATXN3-regulated Hh signaling in tumor formation, we injected mice with MDA-MB-231 cells with or without depletion or overexpression of TSPAN8 in the presence or absence of expression of ATXN3 shRNA." (PMID 31253779, 2019). "We here describe that TEX CD44v6 contributes to tumor progression by cooperating with integrins and proteases and by regulating additional CIC marker, particularly Tspan8, expression in non-CIC." (PMID 27419629, 2016). "Specifically, exosomal CD44v6 promotes tumor progression by increasing mobility, invasion, and anchorage-independent growth of PC cells and is able to modulate the expression of the additional CIC marker tetraspanin Tspan8 in non-CIC cells." (PMID 33803470, 2021).
cancer (84 papers, 2010 to 2025). A tumor composed of atypical neoplastic, often pleomorphic cells that invade other tissues. "Subcluster MTC0 was characterised by high expression of TSPAN8 (encoding tetraspanin 8), which is overexpressed in many cancers, and CD34, a common marker for diverse progenitors." (PMID 38318640, 2024). "TSPAN8 has been implicated in regulating the activity of multiple ADAMs and MMPs, particularly during cancer invasion and metastasis." (PMID 38275818, 2024). "Numerous types of cancers, mainly of the gastrointestinal tract, have been associated with a high level of TSPAN8 expression." (PMID 34830819, 2021). "Tetraspanin Tspan8 function is linked to the regulation of cell motility, and is relevant for cancer progression." (PMID 30982971, 2019). "Another tetraspanin family member, Tetraspanin-8, is also linked to cancer progression by inducing ADAM12 upregulation in esophageal carcinoma promoting metastases." (PMID 29946318, 2018). "In particular, several tetraspanins, such as CD151, TSPAN12, and TSPAN8, among others, have been implicated in cancer initiation, progression and metastasis in mammals." (PMID 25978409, 2015). "Tspan8 is mainly associated with epithelial cells of the digestive tract and its expression appears to be related to poor prognosis in gastrointestinal tumors and other types of cancers." (PMID 37835445, 2023). "The TSPAN8 tetraspanin was initially recognized as a tumor-associated antigen, but further studies proved that its expression is highly correlated with the progression of cancer cells." (PMID 34830819, 2021). "Furthermore, HAUS1, a component of the augmin complex involved in spindle microtubule generation in mitosis and TSPAN8 (also known as CO-029), that encodes for an integrin-binding glycoprotein that stimulates endothelial cell proliferation, are also up-regulated in cancer patients." (PMID 23009291, 2012). "Previous research confirmed that TSPAN8 promotes cancer cell stemness by directly interacting with PTCH1 and enhancing the stability of the SHH-PTCH1 complex." (PMID 41353440, 2025). "Previous research has established Tspan8’s critical role in cancer stem cell characteristic maintenance and the maintenance of stem cell characteristics through Sonic Hedgehog signaling pathway activation." (PMID 40862719, 2025). "The influence of TSPAN8 on cell motility is particularly important in the context of cancer progression." (PMID 40428124, 2025). "The potential roles and interactions of Bcl11b and Tspan8 with Mycn in cancers characterized by Mycn overexpression warrant further investigation." (PMID 40862719, 2025). "Inhibition of TSPAN8 by siRNA led to reduced migration and proliferation of cancer cells, accompanied by a decrease in pERK levels." (PMID 39031113, 2024). "TSPAN8 has been shown to be an important component of exosomes derived from diverse cancer cell types, where its expression is significantly elevated." (PMID 38275818, 2024). "TSPAN8 expression also marks cancer stem cells (CSCs) or cancer-initiating cells (CICs) in various cancer types." (PMID 38275818, 2024). "TSPAN8 expression in cancer cells was also found to promote epithelial-mesenchymal transition (EMT), a key process for cells to acquire the potential to migrate and invade surrounding tissues." (PMID 38275818, 2024). "TSPAN8–integrin interactions promote focal adhesion formation and activate downstream signaling pathways that regulate cytoskeletal rearrangements and cancer cell motility." (PMID 38275818, 2024). "Tetraspanin 8 expression is also elevated in cancer cells exhibiting mesenchymal features, particularly in the triple‐negative breast cancer subtype." (PMID 39031113, 2024). "Given that TSPAN8 is upregulated and partakes in the progression of various cancers, it is crucial to understand the molecular regulation of TSPAN8 transcription." (PMID 38275818, 2024).
cancer (continued). "Circulating EVs overexpressing TSPAN8 have been explored as a non-invasive biomarker for various cancer types and will be discussed in the last section of this review." (PMID 38275818, 2024). "It is important to note that the integrin heterodimers and downstream signaling pathways regulated by TSPAN8 are dependent on the cellular context and the type of cancer." (PMID 38275818, 2024). "The cell-surface expression of TSPAN8 can also be used to target and destroy cancer cells, such as through antibody–drug conjugates or CAR-T (chimeric antigen receptor T-cells)." (PMID 38275818, 2024). "It is important to note that cancer cells have significantly higher tetraspanin 8 expression than normal cells do." (PMID 39031113, 2024). "Nuclear TSPAN8 interacts with the transcription factor STAT3 to activate the transcription of cancer-promoting genes including MYC, BCL-2 and MMP9, which in turn promotes tumorigenesis." (PMID 38275818, 2024). "Based on our TSPAN8 work in the context of cancer, we propose that TSPAN8 as a potential therapeutic target for controlling the severity of COVID-19 disease." (PMID 36827975, 2023). "We have previously reported in cancer cell lines that TSPAN8 increases extracellular vesicle or exosome (EV) numbers and influences their composition." (PMID 36827975, 2023). "TSPAN8, the most downregulated gene, promotes cancer cell stemness via activation of sonic hedgehog signaling, and its expression correlates with a poor prognosis." (PMID 34623465, 2022). "In the same study, we also showed the regulation of cancer-metastasis-related proteins, such as e-cadherin, tetraspanin 8 (Tspan 8), and C-X-C motif chemokine receptor 4 (CXCR4), exerted by SB water extract." (PMID 33918834, 2021). "Consistent with the results of the protein expression levels, quantitative PCR analysis showed that TSPAN8 mRNA levels were significantly upregulated in PDAC cancer cells compared with normal cells." (PMID 34163029, 2021). "In resting stage, the complex of TSPAN8 and integrin localize at the trail of cancer cell; but under PKC signaling simulation, the complex will distribute in a different way." (PMID 34540692, 2021). "A study also showed that TSPAN8 levels promote the progression of cancer stem cells in CRC, a process that is dependent on β-catenin expression." (PMID 34830819, 2021). "A group of researchers used several competition assays with the LEL of TSPAN8 on a CRC cell line along with its knockdown to prove that the LEL is essential in augmenting cancer cell invasion." (PMID 34830819, 2021). "Simultaneously, many murine and human monoclonal antibodies have been generated to evaluate the role of TSPAN8 in cancers for antibody therapy." (PMID 32138170, 2020). "In this review, we will highlight the physiological and pathophysiological roles of TSPAN8 in normal and cancer cells." (PMID 32138170, 2020). "Recently, reports have increasingly shown the functional role and clinical relevance of TSPAN8 overexpression in the progression and metastasis of several cancers." (PMID 32138170, 2020). "In this review, we examined the current status regarding the involvement of TSPAN8 in the development of several cancer types." (PMID 32138170, 2020). "TSPAN8 is highly expressed in various cancerous tissues and mediates the proliferation, survival, invasion and metastasis of cancer cells." (PMID 32138170, 2020). "To date, there is increasing evidence of the development of monoclonal antibodies which are specific to TSPAN8 and their roles in cancer treatment through a variety of in vitro and in vivo efficacy and toxicity evaluation studies." (PMID 32138170, 2020). "To date, several reports have shown that TSPAN8 is a prognostic marker and plays a critical role in the progression and metastasis of cancer cells." (PMID 32138170, 2020). "The aim of this article was to review recent preclinical attempts at targeting tetraspanins in cancer with a focus on Tspan8." (PMID 30769765, 2019).